JAK2 (Janus kinase 2)
Diseases named in the same sentence as JAK2 in open-access papers (continued):
Sharing a sentence is not in itself a finding about the gene and the disease.
ovarian carcinoma (continued). "In this study, for the first time, we discovered that SENP1 directly regulates JAK2 cellular localization via deSUMOylation, and activated SENP1/JAK2 signaling is critical for platinum-resistance in ovarian cancer." (PMID 33795649, 2021). "In ovarian cancer, the activation of JAK2/STAT3 signaling is also correlated with enhanced EMT and a series of malignant phenotypes." (PMID 34895038, 2021). "Our clinical studies demonstrated that SENP1/JAK2 signaling is activated in tumors from platinum-resistant ovarian cancer patients." (PMID 33795649, 2021). "In breast and ovarian cancer, the JAK2/STAT3 signaling pathway is related to the proliferation of cancer stem cells." (PMID 33788424, 2021). "Consistently, the protein levels of SENP1 were also upregulated in platinum-resistant ovarian cancer cells, in which SUMOylation of JAK2 was decreased correspondingly." (PMID 33795649, 2021). "Significantly, this novel SENP1/JAK2 axis is activated in platinum-resistant ovarian cancer in a manner dependent on a transcription factor RUNX2 and activated RUNX2/SENP1/JAK2 is critical for platinum-resistance in ovarian cancer." (PMID 33795649, 2021). "We have found that activated JAK2/STAT/anti-apoptosis signaling leads to platinum-resistance in ovarian cancer cells." (PMID 33795649, 2021). "Previously, our research team reported that adipose stem cells from visceral and subcutaneous fat facilitated the growth and migration of ovarian cancer cells via IL-6/JAK2/STAT3 pathway." (PMID 32121099, 2020). "PEAK1 overexpression activated ERK1/2 and JAK2 signaling pathways and promoted malignant biological behaviors of ovarian cancer cells." (PMID 32167655, 2020). "PEAK1 overexpression activated the ERK1/2 and JAK2 signaling pathways to promote malignant progression of ovarian cancer." (PMID 32167655, 2020). "Together, these results suggest that the dual inhibition of JAK2/STAT3 and AKT demonstrates striking antitumor effect in ovarian cancer cells with PIK3R1 loss." (PMID 30755611, 2019). "We therefore assessed the sensitivity of 3D spheroid ovarian cancer cells to the inhibition of AKT or JAK2/STAT3 signaling." (PMID 30755611, 2019). "More importantly, the blockade of STAT3 phosphorylation with a JAK 2 inhibitor significantly reduced ovarian cancer metastasis in an established genetic mouse model of ovarian cancer." (PMID 31261739, 2019). "In this study, we investigated the therapeutic potential of the JAK1/JAK2 inhibitor ruxolitinib in ovarian cancer treatment, either alone or in combination with conventional chemotherapy agents." (PMID 29849942, 2018). "We demonstrate that paclitaxel treatment enhanced JAK2/STAT3 activation which resulted in the enrichment of cancer stem cell (CSC)-like phenotype in the surviving ovarian cancer cells in vitro and in in vivo mouse xenografts." (PMID 29682172, 2018). "This indicates that leptin can utilize multiple pathways to influence cancer cell migration, although we showed that in ovarian cancer cells inhibition of the JAK2/STAT3 pathway was sufficient to block this effect." (PMID 29212170, 2017). "This study identified leptin-induced migration of LEPR-positive ovarian cancer cells mediated via JAK2/STAT3." (PMID 29212170, 2017). "A role for leptin/LEPR in the survival of ovarian cancer cells was also demonstrated, similarly through the JAK2/STAT3 pathway, consistent with a previous study showing an alternate JAK2 inhibitor was able to induce apoptosis in ovarian cancer cells." (PMID 29212170, 2017). "After silencing Btk gene in ovarian cancer cell lines, we observed that the JAK2 pathway was downregulated." (PMID 26036311, 2015).
ovarian carcinoma (continued). "WP1066, a JAK2 inhibitor, suppresses ovarian cancer growth, migration, and invasion; this inhibitor also enhances the chemosensitivity of ovarian cancer cells and decreases the rate of STAT3 phosphorylation." (PMID 26631279, 2015). "In conclusion, inhibition of IGF-IR and targeting of the JAK2/STAT3 signaling pathway can be a target for ovarian cancer therapy." (PMID 23857432, 2013). "We show that normal and benign ovaries lack overt JAK2 activation, which was only present in low- and high-grade ovarian carcinomas, despite JAK2 expression in normal ovaries, benign, borderline and histological grades of tumours." (PMID 19088723, 2009). "For instance, when paclitaxel was used to treat ovarian cancer cells derived from recurrent patient tumors, it triggered activation of the JAK2/STAT3 signaling pathway and led to elevated expression of CSC-associated genes and proteins in the cells that remained viable." (PMID 40430852, 2025). "Thus, our results indicated that LCP1 can promote EMT by activating the JAK2/STAT3 signaling pathway to promote the resistance of ovarian cancer cells to olaparib." (PMID 39588922, 2024). "miR-503-5p suppression plays a critical role in CD97 expression (a member of the epidermal growth factor (EGF)—seven-transmembrane family, expressed in many cancers) and the related JAK2/STAT3 pathway for enhancing the metastasis of paclitaxel-resistant ovarian cancer cells." (PMID 38139300, 2023). "Previous research also reported that G-CSF may enhance tumor cell migration and impede chemotherapy-induced apoptosis in ovarian cancer cells via the JAK2/STAT3 pathway." (PMID 37298699, 2023). "To explore the application of anti-SENP1/JAK2 for treatment of platinum-resistant ovarian cancer, we found SENP1 deficiency or treatment by SENP1 inhibitor Momordin Ic significantly overcomes platinum-resistance of ovarian cancer." (PMID 33795649, 2021). "Inhibition of JAK2 can reverse the resistance of ovarian cancer to paclitaxel." (PMID 34825509, 2021). "Thus, this study not only identifies a novel mechanism regulating JAK2 activity, but also provides with a potential approach to treat platinum-resistant ovarian cancer by targeting SENP1/JAK2 pathway." (PMID 33795649, 2021). "Furthermore, SENP1-mediated deSUMOylation and the activation of janus kinase 2 (JAK2) promotes platinum resistance in ovarian cancer, which can be overcome by pharmacological inhibition of SENP1 that sensitizes cancer cells to cisplatin." (PMID 34503213, 2021). "Ectopic expression of JAK2 in IGROV1 CR cells with depleted SENP1 restored cisplatin resistance of IGROV1 CR cells to the similar levels as cells treated with control siGL2, suggesting that JAK2 is the primary target of SENP1 to promote platinum-resistance in ovarian cancer cells." (PMID 33795649, 2021). "Macrophage secretory proteins induce ovarian cancer proliferation through the JAK2/STAT3 pathway." (PMID 34109184, 2021). "For instance, melittin induced apoptosis via death receptors and inhibited the JAK2/STAT3 pathway in ovarian cancer cells and also promoted apoptotic cell death via the mitochondrial signaling pathway, but not via the FAS/FASL pathway in human gastric (SCG-7901) cells." (PMID 32823904, 2020). "In addition, it has been shown in ovarian cancer and sarcoma cells expressing constitutively active JAK2 that cisplatin significantly inhibited tyrosine phosphorylation and kinase activity of JAK2 in a dose- and time-dependent manner." (PMID 31929796, 2019). "Inhibition of JAK2/STAT3 signaling pathway induces apoptosis in ovarian cancer cells." (PMID 31540495, 2019). "Leptin stimulation led to increased proliferation, survival and migration of LEPR-expressing ovarian cancer cell lines, with the effects shown to be mediated by the downstream Janus kinase 2/Signal transducer and activator of transcription 3 (JAK2/STAT3) pathway." (PMID 29212170, 2017).
ovarian carcinoma (continued). "This study collectively suggests that leptin/LEPR signaling via JAK2/STAT3 has the potential to significantly impact on pathogenesis in a subset of ovarian cancer patients who may benefit from strategies that dampen this pathway." (PMID 29212170, 2017). "Collectively, our results indicate that administering ibrutinib, as a Btk inhibitor, may facilitate sensitizing ovarian cancer cells to cisplatin through inhibition of the JAK2 pathway." (PMID 26036311, 2015). "In EGF-STAT1 and EGF-STAT3, both gene pairs are involved in pancreatic cancer, EGF pathway, and signal transduction pathway; both STAT1 and STAT3 are activated by the Jak kinase in response to EGF, where JAK2/STAT3 signaling is required for EGF-driven ovarian cancer." (PMID 23940583, 2013). "In contrast, significant inhibition in cell motility was observed within 14 h in EGF-treated cells in the presence of AG490 (100 μM), indicating that JAK2/STAT3 pathway may be involved in the EGF-induced motility of ovarian cancer cells." (PMID 19088723, 2009). "None the less, the pathogenic role of JAK/STAT signalling pathway has been documented in cancer, the role of JAK2/STAT3 in the pathogenesis of ovarian cancer is still unknown." (PMID 19088723, 2009). "Furthermore, combining paclitaxel with the JAK2-selective inhibitor CYT387 in patient-derived ovarian cancer cells suppressed the paclitaxel-induced activation of the JAK2/STAT3 pathway, as well as the expression of CSC and embryonic stem cell markers in the surviving cells." (PMID 40430852, 2025). "In addition, ALKBH5-HOXA10 loop could promote the cisplatin resistance in epithelial ovarian cancer through demethylating JAK2." (PMID 38637813, 2024). "Here, by utilizing high-throughput RNA-Seq-based screening and the related reports on CD97 promotes EMT and metastasis of ovarian cancer cells by activating the JAK2/STAT3 pathway 14, we found that the prometastatic factor CD97 could be a critical mediator of IL-8-induced promotion of EMT." (PMID 37907543, 2023). "In this study, we show that EGF regulates many of the key processes that lead to mesenchymal transition in epithelial ovarian cancer cells and that autocrine signalling through the IL6-R/JAK2/STAT3 pathway is associated with these events and may regulate the metastasis of ovarian carcinoma." (PMID 19088723, 2009). "Our investigation revealed that TWP’s efficacy is driven by its ability to modulate five core targets—EGFR, JAK1, JAK2, PTPN11, and SRD5A1—which our analysis showed to be dysregulated in clinical ovarian cancer datasets." (PMID 41181611, 2025). "Through integrated network analysis and clinical transcriptomic data, we identified five core targets (EGFR, JAK1, JAK2, PTPN11, and SRD5A1) that are differentially expressed in ovarian cancer tissues and serve as central nodes in TWP’s mechanism of action." (PMID 41181611, 2025). "The ALKBH5-HOXA10 loop can mediate JAK2 m6 A demethylation and activate JAK2/STAT3 signaling pathway, facilitating cisplatin resistance in epithelial ovarian cancer (EOC)." (PMID 40483535, 2025). "Based on the results of the experiments and bioinformatics analyses, it is inferred that the target gene CENP-O exerts its effects in ovarian cancer cell disease by regulating genes such as AKT2, JAK2, and MMP9 in SK-OV-3 cells." (PMID 38890751, 2024). "Further research confirmed that GBP5 in ovarian cancer cell can induce canonical pyroptosis through JAK2/STAT1 pathway, thereby restraining the progression of ovarian cancer." (PMID 38817865, 2024). "Specifically, JAK2 upregulation and JAK2/STAT3 pathway activation have critical roles in several solid tumors and significantly influence the survival of patients with ovarian cancers." (PMID 38256218, 2024). "In ovarian cancer, ALKBH5 promotes cisplatin resistance in cancer cells by modifying its m6A target gene JAK2 to activate the JAK2/STAT3 signaling pathway." (PMID 36609413, 2023).
ovarian carcinoma (continued). "A recent study showed that blockade of lncRNA PVT1 reduced the expression of PD-L1 through the JAK2/STAT3 pathway, thereby inhibiting cell proliferation and invasion in cisplatin resistant epithelial ovarian cancer." (PMID 37936074, 2023). "After inhibiting JAK2/STAT3 pathway, the promoting effect of CHAF1A on epithelial ovarian cancer cell proliferation disappeared, meanwhile the inhibitory effect of CHAF1A on apoptosis enhanced." (PMID 37575547, 2023). "In ovarian cancer, the demethylase ALKBH5, which mediates JAK2 m6A demethylation to activate the JAK2/STAT3 signaling pathway, enhances resistance to cisplatin treatment." (PMID 36437944, 2022). "For instance, conditioned media derived from CD45−/CD31− adipose stromal cells, which are isolated from subcutaneous or visceral fat, was shown to activate the JAK2/STAT3 pathway via IL-6 and enhance migration in SKOV3 ovarian cancer cells." (PMID 35565396, 2022). "The IL-6/JAK2/STAT3 pathway has been shown to increase proliferation and migration of ovarian cancer cells, and ovarian cancer patient derived ascites cells, as well as the migration and invasion of breast cancer cells." (PMID 34912237, 2021). "CD97 is a member of the epidermal growth factor (EGF)-seven transmembrane family that signals through Janus-activated kinase 2(JAK2), a signal transducer and activator of transcription 3 (STAT3), to induce paclitaxel resistance in ovarian carcinoma." (PMID 32850313, 2020). "Our results showed that CDC5L (without 3′‐UTR) overexpression reversed the inhibition of malignant behaviors of ovarian cancer cells by miR‐542‐3p and increased the expression levels of PEAK1, p‐ERK1/2, and p‐JAK2." (PMID 32167655, 2020). "In this study, we show a similar up-regulation of activated JAK2/STAT3 pathway, and concomitant significant increase in the expression of CSC-like markers in HEY and TOV21G ovarian cancer cell lines in response to paclitaxel treatment in vitro." (PMID 29682172, 2018). "PLA performed in formalin-fixed paraffin-embedded ovarian cancer tissues clearly demonstrated the interactions between STIP1 and STAT3, STIP1 and JAK2, as well as STIP1 and HSP90 localized mainly in cytoplasm." (PMID 27409672, 2016). "Ovarian cancer tissues were subjected to immunohistochemistry (IHC) and PLA to investigate the in vivo interactions between STIP1 and JAK2." (PMID 27409672, 2016). "The connection between JAK2/STAT3 pathway activation and CSCs has been highlighted in a previous work on ovarian cancer, where the SC marker CD44 together with the embryonic SC marker NANOG have been associated with the activation of STAT3." (PMID 26312765, 2015). "We have recently demonstrated activation of the JAK2/STAT3 pathway and the enhancement of a cancer stem cell (CSC)-like phenotype in ovarian cancer cells treated in vitro with chemotherapeutic agents." (PMID 24782986, 2014). "To investigate that, we analysed the activation status of JAK2/STAT3 in ovarian carcinoma specimens and correlated that to STAT3 activation in two ovarian cancer cell lines directly by EGFR or indirectly through IL-6R activation." (PMID 19088723, 2009). "The relationships between the observed activation of the JAK2/STAT3 pathway in ovarian specimens were correlated with EGF-induced phenotypic changes in OVCA 433 and SKOV3 ovarian carcinoma cell lines." (PMID 19088723, 2009). "We compared the expression and activation status of JAK2 and STAT3 in a range of benign, borderline, and malignant ovarian tumours and normal ovaries, using immunohistochemistry." (PMID 19088723, 2009). "Studies using ovarian cancer cell lines like SKOV3 and PA-1 reported that free melittin treatment upregulates death receptors (DR3, DR4, DR6), activates caspase-3 and caspase-8, and inhibits the pro-survival Janus kinase 2 (JAK2)/STAT3 pathway." (PMID 40871040, 2025).
ovarian carcinoma (continued). "In epithelial ovarian cancer, ALKBH5-HOXA10 loop regulated the methylation of JAK2, which could activate JAK2-STAT3 signaling, thus promoting chemoresistance of cancer cells." (PMID 38637813, 2024). "Additionally, melittin induces apoptosis in ovarian cancer cells by elevating the expression of DR3, DR4, and DR6 death receptors and inhibiting the JAK2/STAT3 signaling pathway." (PMID 38445441, 2024). "•Inhibition of JAK2/STAT3 signaling pathway could reduce the effect of CHAF1A overexpression on the proliferation and growth of epithelial ovarian cancer cells." (PMID 37575547, 2023). "Furthermore, exogenously added IL-6 was shown in a separate study to activate the JAK2/STAT3 pathway and promote migration in SKOV3 and OVCA433 ovarian cancer cell lines." (PMID 35565396, 2022). "In addition, we will construct an ovarian cancer xenograft tumor model and introduce STAT5A or JAK2 recombinant protein to verify the inhibition of MMP2 by high expression of STAT5A, thus affecting the invasion and migration ability of ovarian cancer." (PMID 36524006, 2022). "We aimed to observe the impact of ginkgolic acid (GA) on the proliferation and metastasis ability of ovarian cancer (OCa) cells and to further explore whether GA affects the malignant progress of OCa via regulating the lncRNA MALAT1/JAK2 axis." (PMID 34987594, 2021). "There was a good correlation between SENP1 and phosphorylated JAK2 levels in these tested sensitive and resistant patient tumor samples, indicating SENP1 upregulation is correlated with JAK2-mediated platinum-resistance in ovarian cancer." (PMID 33795649, 2021). "In addition to the in vitro studies, we also demonstrate that paclitaxel treatment significantly enhanced the activation of the JAK2/STAT3 pathway and CSC-like phenotype in the xenografts of mice injected with a serous human ovarian cancer HEY cell line." (PMID 29682172, 2018). "Targeting IL-6, IL-6R or JAK2/STAT3 may offer an efficient management of ascites induced migration and invasion in ovarian cancer patients." (PMID 27825119, 2016). "EGFR and IL-6R signaling cross-talk through JAK2/STAT3 to mediate EMT in ovarian carcinomas; activated STAT3 in high-grade ovarian carcinomas may occur directly through activation of EGFR/IL-6R or indirectly through induction of IL-6R signaling." (PMID 25566498, 2014). "Therefore, the identification of JAK2 activation and increased STAT3 activation in ovarian carcinoma samples is a significant step towards answering this question." (PMID 19088723, 2009). "Previous studies on ovarian cancer cells have shown that melittin inhibits their growth through induction of apoptosis mediated via inhibition of signal transducer and activator of transcription 3 (STAT3) and activation of Janus kinase 2 (JAK2), both of which are critical during angiogenesis." (PMID 27754384, 2016). "We now show that the activation of JAK2/STAT3 may be a pre-requisite for EGF-induced EMT in these ovarian cancer cell lines, as pharmacological inhibition of JAK2 in ovarian cancer cells not only led to an inhibition of STAT3 activation but also inhibition of EGF-induced EMT phenotypes." (PMID 19088723, 2009). "This study investigated whether inhibition of the Janus kinase 2 (JAK2)-signal transducer and activator of transcription 3 (STAT3) pathway by momelotinib is sufficient in suppressing tumor burden and prolonging the disease-free survival period in a mouse model of ovarian cancer." (PMID 29682172, 2018). "Hence, combination therapies that include JAK2/STAT3 and CSC-specific targeted agents and a non-CSC-targeted agent such as chemotherapy, may be a more effective approach for the treatment of ovarian cancer." (PMID 29682172, 2018).